CRP (C-reactive protein)
Diseases named in the same sentence as CRP in open-access papers (continued):
Sharing a sentence is not in itself a finding about the gene and the disease.
Hypertension (continued). "Moreover, hypertension, estimated GFR, peak CK-MB, and C-reactive protein were the other predictors of no-reflow." (PMID 33506051, 2021). "In addition to in-hospital peak glycemia (p < 0.001), the result of the univariate analysis showed that age, hypertension, estimated GFR, peak CK-MB, and C-reactive protein were closely related to the no-reflow phenomenon." (PMID 33506051, 2021). "CRP level was a significant factor of the progression of hypertension in all models (P<0.001); apparently, TNF-α and IL-6 levels are not factors for progression of hypertension." (PMID 28837559, 2017). "Furthermore, hypertension, BMI, the percentage of never smokers, eGFR, albuminuria, AST, ALT, alkaline phosphatase, c-reactive protein, white blood cell count, and the percentage with HBV, HCV, or HIV antibodies were higher across quartiles of the gamma gap." (PMID 26629820, 2015). "Indeed, OSA patients with hypertension show reduced values of IL-10 accompanied by increased levels of TNF-α, IL-6, and CRP with respect to patients without high blood pressure." (PMID 25944984, 2015). "Background/Objective: The C-reactive protein-to-albumin ratio (CAR) reflects both systemic inflammation and nutritional status and has been proposed as a prognostic marker in critical illness, yet its value in intensive care unit (ICU) patients with pre-existing hypertension is not well defined." (PMID 42194645, 2026).
Sepsis (2,359 papers, 2004 to 2026). Sepsis is defined as life-threatening organ dysfunction caused by a dysregulated host response to infection. "Laboratory variables, including low hemoglobin, hypoalbuminemia, elevated C-reactive protein, and increased lactate levels, were also associated with sepsis risk and are supported by existing evidence." (PMID 41598714, 2026). "Infection/sepsis was more frequently the cause of death within five years after HTX among patients with a pre-transplant CRP ≥ 20 mg/L (28.4% vs. 15.8%, p = 0.005), particularly pulmonary infections (19.6% vs. 9.5%, p = 0.006)." (PMID 41753020, 2026). "In the hypoinflammatory phenotype, lower CRP levels were associated with an increased risk of sepsis, likely reflecting immune suppression and insufficient inflammatory response to infection." (PMID 41598714, 2026). "Cord blood CRP ≥3.3 mg/dL and I/T ratio ≥0.155 were significantly associated with sepsis and demonstrated excellent diagnostic performance (area under the curve (AUC): 1.000 and 0.878, respectively)." (PMID 41782789, 2026). "The low specificity and high error rates restrict the clinical utility of CRP for diagnostic or prognostic decision-making in sepsis management." (PMID 41429071, 2025). "Lower serum albumin levels and higher C-reactive protein (CRP) concentrations were independently associated with sepsis (OR = 0.24, 95% CI 0.09–0.62, p = 0.003; OR = 1.013, 95% CI 1.001–1.024, p = 0.027, respectively)." (PMID 41597022, 2025). "C-reactive protein (CRP) and procalcitonin are frequently used as markers of infection and systemic inflammation in liver failure in which sepsis is a common complication and sometimes the cause of mortality." (PMID 41073764, 2025). "Its diagnostic value surpasses that of CRP, suggesting that IL-6 testing should be prioritized in clinical evaluations for suspected sepsis to improve early diagnosis and treatment strategies." (PMID 40242671, 2025). "Although CRP demonstrated high diagnostic accuracy for sepsis, its prognostic utility within sepsis subgroups is limited." (PMID 40864331, 2025). "To date, evidence points to the highly uncertain nature of the use of C-Reactive Protein (CRP) in the diagnostic management or prognostic assessment of adult patients with suspected or already diagnosed sepsis." (PMID 41429071, 2025). "Our study showed that IL-6 is a new biomarker with high sensitivity and good specificity for identifying sepsis, and it has been linked with a better diagnostic value than CRP." (PMID 40242671, 2025). "Our study showed an association between serum AREG levels, CRP levels, and the mortality and severity of patients with sepsis." (PMID 40292295, 2025). "In bacterial infections, elevated CRP levels are associated with disease severity, and CRP is frequently used to assist in the diagnosis of sepsis and pneumonia." (PMID 41010302, 2025). "There is extensive research on biomarkers as potential predictors or having associations with sepsis diagnosis, two of the most common being C-reactive protein and procalcitonin." (PMID 40585595, 2025). "CRP, an acute-phase reactant, is another commonly used marker for systemic inflammation, and higher CRP levels have been linked to worse outcomes in sepsis-related AKI." (PMID 41281283, 2025). "Procalcitonin, together with CRP, is a marker for systemic inflammation and an important diagnostic marker of sepsis that is used for the diagnosis and prediction of the severity of infection." (PMID 40006998, 2025). "This study aimed to evaluate the diagnostic performance of MDW in identifying sepsis compared with other infection markers, including CRP and PCT, in patients who present to the emergency department (ED), particularly those with cancer." (PMID 41303127, 2025). "This study confirms NLPR as a robust prognostic biomarker for sepsis, showing strong associations with key inflammatory and coagulation markers, including CRP, lactate, and D-dimer, as well as decreased albumin and lymphocyte counts." (PMID 40242435, 2025).
Sepsis (continued). "Our primary objective was to systematically and quantitatively assess all published studies regarding the diagnostic application of RETN and CRP levels for sepsis in these populations." (PMID 40416430, 2025). "The incidence of postoperative sepsis was significantly associated with female gender, age ≥60, BMI ≥25 kg/m2, preoperative positive urine culture, and elevated CRP and fasting plasma glucose (FPG) levels." (PMID 40761819, 2025). "Our study revealed high AUCs for both RETN and CRP, indicating that these two biomarkers exhibit enhanced diagnostic accuracy for sepsis." (PMID 40416430, 2025). "CRP is a well-established biomarker for sepsis, while IL-6, a proinflammatory factor, is strongly associated with disease severity and mortality in sepsis." (PMID 40568710, 2025). "Raised CRP concentrations have been associated with several canine diseases involving systemic inflammation, such as sepsis, bacterial pneumonia, and systemic inflammatory response syndrome (SIRS)." (PMID 41472106, 2025). "The combination of these tests increased the diagnostic accuracy of the combination of the WBC count and CRP level, proving useful in the diagnosis of sepsis and comparable to the use of IL-6 and TNF-α." (PMID 40806505, 2025). "Conventional diagnostic techniques for newborn sepsis, including blood culture and laboratory indicators, which include C-reactive protein (CRP) and procalcitonin (PCT), have significant limitations." (PMID 40106759, 2025). "High levels of CRP, as 50 mg/L and more, are related to sepsis and directly associated with organ failure, long duration of ICU stay, and death." (PMID 41007875, 2025). "Several acute phase reactants such as C-reactive protein and procalcitonin have been studied for their diagnostic utility as biomarkers of sepsis." (PMID 40927580, 2025). "Studies have shown that the trajectory of CRP levels is closely linked to mortality in sepsis patients." (PMID 40822945, 2025). "Elevated WBC count, decreased platelet count, and increased CRP levels are well-established biomarkers of systemic inflammation and sepsis, commonly observed in AOPN-associated urosepsis." (PMID 40361922, 2025). "As documented in previous studies, even during sepsis-associated fulminant liver failure with marked inflammatory stimulation, CRP levels tend to remain low." (PMID 40761850, 2025). "Curiously, all three deceased cases had systemic inflammatory response syndrome (fever, leukocytosis, elevated CRP) associated with multiorgan failure (sepsis) and a critical severity score." (PMID 40552167, 2025). "While consecrated molecules such as C-reactive protein, procalcitonin, and presepsin perform well in practice, there is still a need for more specific diagnostic and predictive biomarkers for sepsis and related organ dysfunction." (PMID 40429966, 2025). "PSP demonstrated good diagnostic accuracy for sepsis with a sensitivity of 84% and specificity of 82%, outperforming both MR-proADM (Mid-Regional pro-Adrenomedullin) and CRP." (PMID 40647525, 2025). "Procalcitonin demonstrated superior diagnostic accuracy compared with C-reactive protein and interleukin-6 for the early detection of postoperative sepsis following lung decortication." (PMID 41281040, 2025). "Although it only has moderate specificity for early identification of sepsis, previous studies showed that markedly elevated CRP level was associated with an increased risk of septic shock in children." (PMID 41291834, 2025). "Risk factors for postoperative sepsis in this patient population include older age, female gender, higher BMI, preoperative urine culture positivity, and elevated CRP and FPG levels." (PMID 40761819, 2025). "Elevated CRP levels have been associated with worse outcomes and higher mortality rates in sepsis, while higher cfDNA levels are strongly correlated with disease severity, organ failure, and mortality." (PMID 40282303, 2025).
Sepsis (continued). "In contrast, higher levels of CRP, procalcitonin, and ferritin were observed, markers associated with systemic inflammation, sepsis, and cytokine release syndrome." (PMID 41210231, 2025). "Among the score components, elevated CRP (OR 1.15, 95% CI 1.10-1.21) and elevated creatinine (OR 4.31, 95% CI 1.50-12.40) were independently associated with sepsis diagnosis." (PMID 41573561, 2025). "In human medicine, CAR has shown strong diagnostic and prognostic value in sepsis, cancer, and critical illness, often outperforming CRP or albumin alone in predicting outcomes." (PMID 41472106, 2025). "Laboratory tests showed leukocytosis (16.08 × 109/L) and elevated inflammatory markers—erythrocyte sedimentation rate (ESR) 77 mm/h and C-reactive protein (CRP) 214.1 mg/L—while procalcitonin (PCT) remained within the low-risk range for sepsis (0.22 μg/L)." (PMID 41440229, 2025). "We conclude that the diagnostic performance of calprotectin in identifying sepsis patients at ICU admission was inferior to that of CRP." (PMID 40319081, 2025). "Elevated IL-18 levels have been consistently associated with sepsis severity and poorer outcomes in critically ill patients, outperforming conventional markers like procalcitonin and CRP in diagnostic utility in some studies." (PMID 40722817, 2025). "On DOL 9, the baby had abdominal distension associated with bilious aspirates; a sepsis workup showed rising levels of CRP and thrombocytopenia; antibiotics were upgraded further." (PMID 40948504, 2025). "In comparison to other biomarkers, cfDNA and MPO provide an additional diagnostic value to CRP for sepsis diagnosis." (PMID 40731775, 2025). "They found that infants with NEC-associated sepsis had significantly higher CRP levels and lower platelet counts at NEC onset and 24 h after onset compared to those without sepsis." (PMID 40726903, 2025). "MR-proADM is a more reliable marker than procalcitonin (PCT) or C-reactive protein (CRP) for assessing prognosis and mortality risk in patients with sepsis admitted to intensive care units." (PMID 40149646, 2025). "The authors concluded that elevated serum CRP levels were associated with an increased risk of developing sepsis as well as with higher rates of persistence and recurrence of the PJI." (PMID 40867947, 2025). "CRP is a well-established inflammation marker linked to increased all-cause mortality, including sepsis-related deaths." (PMID 40500114, 2025). "Elevated CRP levels are associated with sepsis and can be used as a marker to monitor the progression and severity of the infection." (PMID 40667510, 2025). "Serial measurements of CRP combined with other acute phase reactants and diagnostic sepsis markers will improve its overall diagnostic accuracy." (PMID 40224545, 2025). "Sepsis diagnosis was based on a suspicion of infection and combination of clinical symptoms or risk factors aided where possible by a CRP test, blood cultures and confirmed by an independent clinician’s diagnosis." (PMID 39937751, 2025). "This study investigated plasma sLOX-1 levels in patients with SIRS, sepsis, or septic shock, examining associations with CRP and PCSK9 levels, disease severity, SARS-CoV-2 infection, and underlying liver cirrhosis." (PMID 39948564, 2025). "A detailed analysis of patients' demographic and clinical profiles revealed statistically significant differences between deceased and discharged patients regarding the presence of underlying oncologic pathology, sepsis status, and levels of IL-6 and CRP." (PMID 41011807, 2025). "In this study, the ROC curve analysis revealed that plasma CRP level exhibited the poorest diagnostic performance, with low specificity in the early diagnosis of sepsis in children." (PMID 40895306, 2025). "In patients with malignancy, PCT and MDW showed comparable diagnostic accuracy for sepsis under Sepsis-3 criteria (AUCs of 0.853 and 0.852, respectively), whereas CRP yielded a lower AUC of 0.734." (PMID 41303127, 2025).
Sepsis (continued). "Neutropenia, in turn, was associated with sepsis, higher inflammatory markers (CRP, PCT, and cortisol), and higher disease severity (SAPS)." (PMID 41155261, 2025). "We also showed that irisin was negatively associated with most inflammatory biomarkers (CRP, procalcitonin, IL-6, IL-10) at sepsis onset, in accordance with in vitro studies." (PMID 38540711, 2024). "While serum CRP remains a standard diagnostic tool, debates surrounding its accuracy in late-onset sepsis prompt considerations for the usefulness of salivary CRP as a diagnostic marker for neonatal pneumonia." (PMID 38741881, 2024). "This was confirmed by higher TLC and CRP which are the precise indicators of sepsis, denoting that sepsis is an important risk factor for developing neonatal thrombosis." (PMID 39349608, 2024). "In an exploratory analysis, the magnitude of the inflammatory response following BSI, measured by peak CRP, was associated with 30-day sepsis mortality." (PMID 38680606, 2024). "The results of this study indicate that CRP and cf-DNA are independent risk factors for sepsis in both the sepsis and non-sepsis groups, demonstrating moderate diagnostic value." (PMID 39457503, 2024). "To confirm our suspicions, we included clinical information and HOTTIP levels in a logistic regression analysis and found that HOTTIP and COPD, respiratory infection, and CRP were all independent predictors of the risk of ARDS in patients with sepsis." (PMID 38238652, 2024). "Our findings indicate that DM, higher SI, higher NLR, and increased levels of CRP are significantly associated with a higher likelihood of sepsis." (PMID 39064542, 2024). "IL-10 and NEWS had the strongest association with sepsis development, whereas IL-6 and CRP had the strongest association with ICU admission and in-hospital mortality." (PMID 39212218, 2024). "Within a meta-analysis including 9 studies and 1,368 patients, CRP was shown to have a moderate accuracy for the diagnosis of sepsis (area under the curve (AUC) = 0.73), while the diagnostic accuracy of procalcitonin (PCT) was higher (AUC = 0.85)." (PMID 37204560, 2024). "A significant portion, 87.5%, present with sepsis, highlighting the need for early diagnostic measures, including blood and urine cultures, as well as monitoring of lactate, CRP, and ESR to assess systemic involvement." (PMID 39280445, 2024). "CRP, acknowledged as an acute-phase inflammatory marker indicative of the acute phase of sepsis, confirmed its diagnostic utility in our study." (PMID 38667467, 2024). "Among the array of inflammatory markers, the diagnostic accuracy of PCT and CRP in bacterial infection and sepsis has been extensively studied." (PMID 38438974, 2024). "CRP, anemia, PRBCs-transfusion and sepsis were previously discussed as risk factors for ROP, and enhanced growth as a protective factor for ROP in the primary outcome." (PMID 39427215, 2024). "We aimed to study the diagnostic significance of conventional (PCT and CRP) and new (IL-10) markers in accurately identifying sepsis and assessing its progression toward irreversible sepsis, shock, and multiorgan dysfunction." (PMID 39507174, 2024). "Both C-reactive protein (CRP) and cf-DNA were identified as independent risk factors for sepsis, demonstrating moderate diagnostic value." (PMID 39457503, 2024). "In recent years, efforts to improve the management of sepsis have focused on the development of early warning systems and diagnostic algorithms that incorporate biomarkers like CRP and PCT." (PMID 39469363, 2024). "In a multicenter study of children with severe sepsis, persistent lymphopenia was associated with organ failure and death and higher maximal CRP levels." (PMID 38410766, 2024). "Procalcitonin was elevated at 8.94 ng/mL, indicating a high risk for sepsis, and C-reactive protein (CRP) was 83 mg/L." (PMID 39280445, 2024).